PTCH1 (patched 1)
Diseases named in the same sentence as PTCH1 in open-access papers (continued):
Sharing a sentence is not in itself a finding about the gene and the disease.
gastric cancer (continued). "MSP amplification detection and DNA sequencing showed that multiple sites of CpG island hypermethylation existed in the PTCH1 gene of the gastric cancer cell line." (PMID 24255663, 2013). "To gain insight into the causal role of the hedgehog pathway in gastric cancer, we sequenced the full length coding region of both SMO and PTCH1 genes in a panel of 39 gastric tumors of different histologic subtypes." (PMID 23349881, 2013). "In conclusion, this study showed that the PTCH1 gene expression in a gastric cancer cell line was reduced." (PMID 24255663, 2013). "The aim of this study was to investigate the correlation between patched 1 (PTCH1) expression and its methylation in a human gastric cancer cell line, in order to provide new information regarding carcinogenesis and the development of gastric cancer." (PMID 24255663, 2013). "In the present study, qPCR and immunocytochemical staining were used to detect PTCH1 expression in the AGS gastric cancer cell line." (PMID 24255663, 2013). "This indicated that the PTCH1 gene of the AGS gastric cancer cell line had undergone methylation in the CpG island." (PMID 24255663, 2013). "In the present study, MSP amplification was performed to detect the CpG island methylation status of the PTCH1 gene in the AGS gastric cancer cell line." (PMID 24255663, 2013). "High‐stage gastric cancer and negative PTCH1 staining have been identified as unfavourable risk factors for overall survival, and an important role for Hh signalling in bladder cancer growth and tumourigenicity has been described." (PMID 33713376, 2021). "PTCH1 blocks pathway activity in non-stimulated cells, and its loss due to methylation was observed in breast and gastric cancers and colorectal precancerous lesions." (PMID 27553089, 2017). "In the present study, the expression of PTCH1 mRNA was detected in gastric cancer tissues, adjacent normal tissues and a human gastric cancer cell line, with a relatively high expression of PTCH1 mRNA in the adjacent normal tissues compared with the cancer tissues." (PMID 25013484, 2014). "This indicates that the high methylation modification of PTCH1 as a tumor suppressor gene may be one of the main mechanisms of gastric cancer." (PMID 25013484, 2014). "The present study aimed to investigate the role of PTCH1 methylation in gastric carcinogenesis and the therapeutic effect of the methylation inhibitor, 5-aza-2′-deoxycytidine (5-aza-dC), in the treatment of gastric cancer." (PMID 25013484, 2014). "This indicated the presence of high PTCH1 gene methylation in the gastric cancer tissues." (PMID 25013484, 2014). "However, the correlation between the methylation of PTCH1 and gastric cancer has rarely been explored." (PMID 24255663, 2013). "This suggested a low level of PTCH1 expression in gastric cancer." (PMID 24255663, 2013). "The methylation zone in the gastric cancer cell line was different from those of previous studies, indicating that the high-methylation mechanism of the PTCH1 gene promoter may be different for different types of carcinogenesis." (PMID 24255663, 2013). "In the present study, the expression of PTCH1 in a human gastric cancer cell line was investigated prior to and following treatment with a methylation inhibitor, in order to explore the correlation between PTCH1 expression and the CpG island methylation of the gene promoter region." (PMID 24255663, 2013). "In conclusion, the high level of methylation in the PTCH1 gene promoter region may be involved in carcinogenesis and the development of gastric cancer, and may provide a new biomarker for gastric cancer." (PMID 24255663, 2013). "Gastric cancer cells exhibit both increased sonic hedgehog (SHH) expression and higher levels of Patched 1 (PTCH1) receptor." (PMID 40149274, 2025). "In order to observe the incidence of PTCH1 gene methylation in the gastric cancer tissues, MSP detection was conducted in the gastric cancer and adjacent normal tissues of 20 patients." (PMID 25013484, 2014).
gastric cancer (continued). "To assess potential DNA alterations of the hedgehog pathway in gastric cancer, we sequenced SMO and PTCH1 genes in a set of 39 gastric tumors." (PMID 23349881, 2013). "Based on the qPCR, no amplified strip was observed in the control AGS gastric cancer cell line without the treatment of 5-Aza-dc, indicating that there was no expression of PTCH1 mRNA present." (PMID 24255663, 2013). "The methylation status of the promoter region of the PTCH1 gene in the AGS gastric cancer cell line was examined using methylation-specific PCR (MSP), while CpG island methylation in the PTCH1 gene 5′ regulatory sequence was analyzed using DNA methylation analysis software." (PMID 24255663, 2013). "Treating gastric cancer AGC cell line with 5aza-dC effectively reduced cell viability and induced apoptosis, suggesting a role of canonical Hh pathway activation in gastric tumorigenesis through hypermethylation and subsequent downregulation of the PTCH1 and HHIP negative regulators." (PMID 34572373, 2021). "The expression of PTCH1 mRNA and protein was absent in the AGS gastric cancer cell line prior to 5-Aza-dc treatment." (PMID 24255663, 2013).
liver fibrosis (15 papers, 2015 to 2025). "Patched1 (PTCH1), a negative regulatory factor of the Hh signalling pathway, was down-regulated during liver fibrosis and associated with its hypermethylation status." (PMID 26257392, 2015). "Hh signaling pathway and PTCH1 gene hypermethylation are closely associated with cell proliferation and liver fibrosis, and these findings may be applied to the diagnosis and treatment of patients with liver fibrosis." (PMID 37056286, 2023). "Specially, ALKBH5 can suppress hepatic stellate cell (HSC) activation and ameliorate liver fibrosis by triggering Patched 1 (PTCH1) activation and decreasing Dynamin-related protein 1 (Drp1) methylation in a m6A dependent fashion." (PMID 38545555, 2024). "Yang and colleague reported that DNA hypermethylation of Ptch1 was involved in decreased Ptch1 expression during rats’ hepatic fibrosis." (PMID 36594057, 2023). "Firstly, in vitro activation of HSCs and CCl4-induced liver fibrosis models in mice showed that PTCH1 affects HSC activation through the Gli1 and Smad3 signaling pathways." (PMID 37056286, 2023). "Our previous study showed that microRNA-152 (miR-152) inhibits liver fibrosis by attenuating DNA methyltransferase 1(DNMT1)-mediated PTCH1 methylation." (PMID 27588491, 2016). "Given the importance of Hh signaling in mediating T cell development and cytotoxic functions, and its enrichment as leading GSEA hit, we confirmed differential RNA expression in CD8 T cells in disparate liver fibrosis severities in HCV infection by qPCR analysis of PTCH1, SMO, and GLI1 mRNA." (PMID 38887299, 2024). "We also identify PVT1/miR-152/PTCH1 as a new signaling network in liver fibrosis." (PMID 27588491, 2016). "In vitro and in vivo models, including HSCs and clinical cases or CCl4-induced mice liver fibrosis, ALKBH5 triggered PTCH1 activation in an m6A-dependent manner, leading to hedgehog signaling inactivation, which inhibited the transformation of HSCs into myofibroblasts and ameliorated liver fibrosis." (PMID 39220683, 2024). "Upregulation of PTCH1 leaded to inactivation of the Hedgehog signaling pathway, inhibiting HSC activation and ameliorating liver fibrosis." (PMID 39220683, 2024). "In the same context, the current results reveal the correlation between the hepatic fibrosis prompted by DEN and the marked stimulation of Hh signaling, as clarified by the amplified gene expressions of Ptch1 as well as Gli1 and Gli2." (PMID 36811777, 2023). "Previously, we found that microRNA-152 (miR-152) epigenetically up-regulated Patched1 (PTCH1) expression, resulting in the suppression of the epithelial–mesenchymal transition (EMT) during liver fibrosis." (PMID 37397418, 2023). "Previously, we demonstrated that miR-152 promotes PTCH1 demethylation by inhibiting DNMT1, thereby controlling liver fibrosis." (PMID 37397418, 2023). "When PTCH1 is hypermethylated, PTCH1 expression is downregulated and HSCs are activated, while ALKBH5 upregulates PTCH1 expression and improves or alleviates liver fibrosis." (PMID 37056286, 2023). "PVT1 activates the Hedgehog pathway by enhancing the methylation of Patched1 (PTCH1) and down-regulating PTCH1 expression through competitively binding miR-152, which is a driver of EMT and HSC activation in liver fibrosis." (PMID 33933107, 2021). "PVT1 also activates the Hedgehog pathway by enhancing the methylation of Patched1 (PTCH1) and down-regulating PTCH1 expression through competitively binding miR-152, which is a driver of EMT and HSC activation in hepatic fibrosis." (PMID 32326098, 2020). "In conclusion, we demonstrate that PVT1 can epigenetically inhibit PTCH1 via competitively binding miR-152, contributing to activation of Hh pathway and EMT process in liver fibrosis." (PMID 27588491, 2016). "Collectively, we demonstrate that PVT1 epigenetically down-regulates PTCH1 expression via competitively binding miR-152, contributing to EMT process in liver fibrosis." (PMID 27588491, 2016).
liver fibrosis (continued). "Collectively, miR-152 induced by Sal B, contributed to DNMT1 down-regulation and epigenetically regulated PTCH1, resulting in the inhibition of EMT in liver fibrosis." (PMID 26257392, 2015).
prostate carcinoma (14 papers, 2004 to 2025). A carcinoma that arises from epithelial cells of the prostate gland. "Furthermore, Ptch1 expression has been proposed to be an early marker for gastric and thyroid cancers, and more recently a prognosis marker for relapse in high-risk prostate cancer patients." (PMID 35631574, 2022). "To demonstrate the role of hedgehog pathway in prostate cancer, we screen five available cell lines for the expression of Gli1, PTCH1 and HIP." (PMID 15482598, 2004). "All these data indicate that the hedgehog pathway is activated in advanced prostate cancers, as indicated by high expression of PTCH1 and HIP." (PMID 15482598, 2004). "However, increased expression of PTCH1 was detected in several cancers including ovarian carcinoma, lung, and prostate cancer." (PMID 37700842, 2023). "In prostate cancers with Gleason scores 3–6, 4 out of 18 specimens were positive for PTCH1 (22%), whereas 16 out of 22 undifferentiated carcinomas (Gleason Scores of 8–10) expressed PTCH1 (73%), suggesting that the hedgehog pathway is frequently activated in advanced prostate cancer." (PMID 15482598, 2004). "Using PTCH1 antibodies, we examined 59 prostate cancer samples for hedgehog signaling activation." (PMID 15482598, 2004). "Components of the SHH pathway, including GLI1 (GLI family zinc finger 1), PTCH1 (protein patched homolog 1), and SHH, are highly up-regulated in human prostate cancer tissues, compared with prostatic epithelium." (PMID 36969009, 2023). "PTCH1 and RDX are other 2 genes shared by our breast and prostate cancer cells, both are targeted by multiple miRNAs." (PMID 34157951, 2021). "In prostate cancer, treatment with Gant61 induced suppression of tumor growth with decreased GLI1 and PTCH1 expression." (PMID 33396427, 2020). "In a human prostate cancer xenograft model in mice, GANT-61 reduced tumor growth and proliferation and strongly reduced expression of PTCH1 mRNA." (PMID 26891329, 2016). "Studies have also shown that in LNCaP prostate cancer xenografts mouse models, TAK-441 delayed castration-resistant progression of the disease and significantly suppressed GLI1, GLI2, and PTCH1 gene expression." (PMID 26891329, 2016). "Protein expression of the hedgehog signaling-pathway components SHH, PTCH1, GLI1, and GLI2 was also generally reduced in OLFM4-expressing prostate-cancer cells compared with control vector-transfected cells." (PMID 26581960, 2015). "We found that expression of the hedgehog-signaling components SHH, PTCH1, and GLI1 was reduced between 30–70% in OLFM4-expressing prostate-cancer cells compared with control vector-transfected cells." (PMID 26581960, 2015). "In prostate cancer, the mRNA levels of SHH, PTCH1 and GLI1 were highly elevated in more advanced stages of the cancer, and all those components were closely linked to Gleason score." (PMID 25369201, 2014). "High levels of Sonic Hedgehog activity, as monitored by PTCH1, GLI1 or HIP expression, are present in all metastatic prostate cancer samples that have been tested." (PMID 16507112, 2006). "Immunohistostaining with HIP antibodies in prostate cancer specimens revealed a similar pattern to prostate specific antigen (PSA) and PTCH1, further confirming that hedgehog pathway is activated in advanced prostate cancers." (PMID 15482598, 2004). "Of the 16 PTCH1 positive prostate cancer specimens with Gleason scores 8–10, 9 have no detectable Su(Fu) protein." (PMID 15482598, 2004). "In total, 11 of 27 PTCH1 positive prostate cancer specimens have no detectable Su(Fu) protein." (PMID 15482598, 2004).
holoprosencephaly (12 papers, 2013 to 2024). Holoprosencephaly (HPE) is a complex brain malformation resulting from incomplete cleavage of the prosencephalon, occurring between the 18th and 28th day of gestation, and affecting both the forebrain and face, which results in neurological manifestations and facial anomalies of variable severity. "Conversely, loss-of-function mutations of Ptch1 lead to holoprosencephaly, a characteristic phenotype of reduced Hh signaling." (PMID 38201225, 2023). "The proper function of Cdon requires its interaction with both Shh and Ptch1, as mutations disrupting Cdon-Ptch1 interaction results in holoprosencephaly." (PMID 38201225, 2023). "GLI2, SHH, and PTCH1 represent key hedgehog pathway members, which are critical for craniofacial patterning, and variations in these genes have been associated with holoprosencephaly with CL/P." (PMID 37745857, 2023). "AD, PD, and MG all had SNPs in PTCH1 (associated with holoprosencephaly) and XKR9 (associated with otofaciocervical syndrome)." (PMID 35711735, 2022). "PTCH1 mutations are also described in patients with holoprosencephaly." (PMID 29575684, 2018). "We also identified variants in the holoprosencephaly associated genes GLI2 and PTCH1." (PMID 38096238, 2023). "Decreased SHH signaling (either through haploinsufficiency for SHH or by increasing the repressive activity of PTCH1) has severe developmental consequences that mirror human holoprosencephaly (HPE), a common forebrain defect resulting from the failure of the cerebral hemispheres to separate." (PMID 26935104, 2016).
meningioma (12 papers, 2019 to 2025). A generally slow growing tumor attached to the dura mater. "In our cohort, N6 meningioma with intact chr1p, but where one copy of PTCH1 has a 104G>A mutation resulting in R35Q amino acid change in PTCH1, clustered on a PCA plot with tumors which lost chr1p." (PMID 36937440, 2023). "Collectively, our RNA-Seq results provide strong evidence for activation of Hh signaling among meningiomas that harbor relevant genomic mutations in SMO or PTCH1, or events near 2q35 or 7q36.3." (PMID 37805627, 2023). "We confirmed known associations, such as PTCH1 with MB, SMARCB1 with ATRT, and SMARCE1 with meningioma (MNG)." (PMID 39974082, 2025). "We found that all the samples that acquired those SVs clustered with meningiomas harboring known Hh activating events (cluster 1, which we call the Hh cluster), such as a recurrent mutation SMOL412F and a damaging one in PTCH1 (ENST00000331920.6:c.1503+3A>G)." (PMID 37805627, 2023). "Due to the low incidence of meningioma in PTCH1 PV carriers, specific screening procedures for this tumor are not required." (PMID 33860896, 2021). "Aberrant signaling in the sonic hedgehog (SHH) pathway caused by mutations in PTCH1, PTCH2, and SUFU genes, located at 9q22.32, 1p34.1, and 10q24.32, respectively, with PTCH1 being the most common, increases the risk of meningioma development." (PMID 33801089, 2021). "Brain MRI for meningiomas and pelvic ultrasound for ovarian fibromas should be offered to both PTCH1 and SUFU PV carriers." (PMID 33860896, 2021). "Patients with SUFU mutations are more likely to develop meningiomas compared to PTCH1 or PTCH2 mutations even with the absence of PTCH mutation, which have been found in families with hereditary multiple meningiomas." (PMID 33801089, 2021). "Indeed, in the Manchester cohort, the incidence of meningiomas was much higher in SUFU PV carriers (4/9) than in patients with a PTCH1 PV (2/126)." (PMID 33860896, 2021). "Meningiomas are probably more frequent in SUFU related GS than in PTCH1 related GS." (PMID 33860896, 2021).
odontogenic keratocysts (12 papers, 2012 to 2025). "In people with Gorlin syndrome, they carry an inactivating germline mutation of one allele of the PTCH1 gene that predisposes them to multiple developmental abnormalities such as odontogenic keratocysts and skeletal anomalies." (PMID 34572373, 2021). "Conversely, PTCH1 mutations present a stronger association with odontogenic keratocysts." (PMID 35096710, 2021). "It is noteworthy that neither odontogenic keratocysts nor cardiac fibromas occurred in the present series, with both tumours being hallmarks of PTCH1-associated GS." (PMID 35768194, 2022). "The two families (NBCCS_N and NBCCS_O) without a disease‐associated mutation, in PTCH1 or other candidate genes, had no unusual NBCCS clinical phenotypes; both families had BCC, palmoplantar pits, odontogenic keratocysts, and falx cerebri calcifications." (PMID 30411536, 2018).